AHR (aryl hydrocarbon receptor)
Diseases named in the same sentence as AHR in open-access papers (continued):
Sharing a sentence is not in itself a finding about the gene and the disease.
breast carcinoma (continued). "In contrast, high AhR content has been reported to promote proliferation in a human MCF breast cancer cell line that was blocked by the AhR antagonist MNF or selective AhR knockdown via small interfering RNA." (PMID 20570779, 2010). "Supporting the activity of tranilast as an AHR agonist we find that: 1) It strongly induces CYP1A1 expression (a classic marker of AHR activity) in breast cancer cells." (PMID 21072210, 2010). "DIM is a selective AhR modulator found in cruciferous vegetables that has been studied as a possible chemopreventive agent for treating breast cancer." (PMID 20435555, 2010). "Recent studies suggest that the AHR is an excellent target for breast cancer therapy, and tranilast appears to be an exceptional drug for this purpose." (PMID 21072210, 2010). "Recent reports indicate the existence of breast cancer cells expressing very high levels of the Arylhydrocarbon receptor (AhR), a ubiquitous intracellular receptor best known for mediating toxic action of dioxin and related pollutants." (PMID 19604390, 2009). "Inhibitory AhR-ER cross-talk has been demonstrated in breast cancer cells, rodent uterus and mammary tumors." (PMID 17433103, 2007). "Inhibitory AhR and ER cross-talk have also been demonstrated in breast cancer cells, rodent uterus and mammary tumors." (PMID 17433103, 2007). "Because it is an AhR inhibitor, it seemed plausible that galangin has the potential to block formation of mutagenic metabolites in tumor cells and to regulate human mammary cancer cell proliferation." (PMID 16569260, 2006). "Notably, FOXA1 and RAB25 are strongly implicated in breast cancer biology, and FOXA1 has been directly linked to the aryl hydrocarbon receptor (AHR), the main regulator of CYP1A1." (PMID 41901204, 2026). "Furthermore, indole and their derivatives can act as endogenous ligands to activate AhR, a poor prognosis marker of breast cancer." (PMID 41491244, 2026). "To test whether the AHR activation can boost degradation-targeted PARP7-mediated ADPr in a different cell line, we used wild type and PARP7-deficient breast cancer MCF7 cells generated previously." (PMID 41326691, 2026). "In patients with ER+ breast cancer, the prognostic impact of AhR is context dependent." (PMID 40646277, 2025). "Among patients who self-reported alcohol abstention, AHR_1 Any T carriers had a non-significant decreased risk for breast cancer events compared with AHR_1 CC carriers." (PMID 40646277, 2025). "The aryl hydrocarbon receptor mediates the proliferation of breast cancer cells through DEHP." (PMID 41301867, 2025). "For example, quercetin is a weak agonist for AhR in T47D breast cancer cells." (PMID 40137111, 2025). "Furthermore, AhR interacts with coordinators of inflammatory response and breast cancer inducing factors such as nuclear factor kappa-light-chain-enhancer of activated B cells (NF-κB)." (PMID 40646277, 2025). "None of the AHR SNPs were associated with breast cancer events (all P values ≥ 0.070) or overall survival (all P values ≥ 0.24)." (PMID 40646277, 2025). "Studies indicate that AhR promotes breast cancer malignancy." (PMID 38792249, 2024). "We propose that AHR in the PMN may be a potential therapeutic target to limit breast cancer lung metastasis." (PMID 39690159, 2024). "In addition, mexiletine exhibits AHR antagonist activity in human MDA-MB-468 breast cancer cells but acts as an AHR agonist in rat hepatoma cells." (PMID 39450255, 2024). "Similarly, inactivation of AhR in cancer stem cells in a breast cancer model sensitized tumors to the chemotherapy doxorubicin." (PMID 38339226, 2024). "AHR is upregulated and constitutively active in many different cancer types, including neck squamous cell carcinoma, non-small cell lung cancer, colorectal cancer, and breast cancer." (PMID 39450255, 2024). "Thus, there is consistent evidence from multiple laboratories that AhR is tumor suppressive in ER+ breast cancer cells." (PMID 38807762, 2024).
breast carcinoma (continued). "In breast cancer, AHR activation reduces the proliferation of estrogen receptor-positive breast cancer cells, while both AHR agonists and antagonists have been reported to reduce colony formation, migration and metastasis of triple negative breast cancer cell lines." (PMID 39450255, 2024). "Finally, AHR potential involvement in modulating IL-8, a critical gene that mediates breast cancer invasion and metastasis to the lungs, was also highlighted." (PMID 38982523, 2024). "Therefore, a comprehensive investigation into the molecular mechanisms underlying STAT5 signaling in the regulation of the proteasome will enhance our understanding of the changes in AHR in macrophages within the PMN of breast cancer." (PMID 39690159, 2024). "In addition to the effect of IS, direct upregulation of Hes1 expression through the AhR, independent from Notch, was observed in human mammary carcinoma cells." (PMID 39201457, 2024). "The AhR has been reported to induce Hes1 expression in mammary carcinoma and liver cells." (PMID 39201457, 2024). "In agreement with this dilemma, it has also been proposed that the activation of AhR could modulate the response of tumor cells to antitumor chemotherapy in breast cancer either positively or negatively." (PMID 38745771, 2024). "For instance, AHR activation by the tryptophan metabolite kynurenine promotes malignant migration in human glioma cells, while omeprazole inhibits tumor migration in breast cancer via the AHR-CXCR4 pathway." (PMID 39125717, 2024). "As in breast cancer, these data may be partly explained by inhibitory crosstalk of the AhR signaling pathway with the estrogen receptor (ER) pathway." (PMID 38807762, 2024). "Notably, the mechanism by which IL1B regulates IL-8—a critical gene that mediates breast cancer invasion and metastasis to the lungs —and the role of AHR in such mechanism, is worth pursuing." (PMID 38982523, 2024). "The aryl hydrocarbon receptor (AHR) is constitutively active in advanced breast cancer tumours." (PMID 39282472, 2024). "Interestingly, increased ROS levels in the TME can trigger the production of antioxidant proteins by activating AhR, thereby shielding breast cancer cells from oxidative stress." (PMID 38434684, 2024). "Thus, the positive regulatory role of AHR on PD-L1 level during breast cancer progression specifically occurs in lung macrophages." (PMID 39690159, 2024). "It is worth investigating whether AhR activation promotes or hinders tumor formation, and studies on breast cancer have readily demonstrated this paradox." (PMID 38434684, 2024). "Studies in breast cancer have revealed complex tumor regulatory functions for AhR." (PMID 38807762, 2024). "This suggests that AhR may serve as a relay for pro- or oncogenic factors, and its binding to various AhR ligands helps control the growth and migration of breast cancer cells." (PMID 38434684, 2024). "Additionally, our analysis using the Kaplan-Meier Plotter online tool showed a correlation between AHR expression and the overall survival (OS) of breast cancer patients." (PMID 39690159, 2024). "Moreover, in the last 10 years, the role of the AHR as a therapeutic target in cancers has emerged in particular through the involvement of agonists and inhibitors in breast cancer, hepatocellular carcinoma, and melanoma." (PMID 39336758, 2024). "Thus, AhR expression alone plays various roles in breast cancer depending on the ligand to which it binds and its effects on different cell types." (PMID 38434684, 2024). "AhR knockdown resulted in the induction of apoptotic death in breast cancer cells." (PMID 37830596, 2023). "Our findings suggest that the AhR-mediated expression of IDO2 in breast cancer could contribute to a pro-tumorigenic microenvironment in breast cancer." (PMID 37408267, 2023).
breast carcinoma (continued). "However, we also observed that AHR undergoes LAMP2A-mediated degradation in the triple-negative MDA-MB-468 human breast cancer cells, revealing that AHR can undergo different autophagy mechanisms in a cell-specific manner." (PMID 37894798, 2023). "In The Cancer Genome Atlas (TCGA) and Genomic Spatial Event (GSE) databases, we found that a higher expression of AHR was correlated with a worse prognosis in patients with several cancer types, including breast cancer, lung cancer, glioma, and pancreatic adenocarcinoma." (PMID 38099490, 2023). "Moreover, TAX improved dimethylbenzanthracene (DMBA)-induced mammary carcinoma via down-regulating the aryl hydrocarbon receptor (AhR) signaling pathway." (PMID 36740800, 2023). "It has been shown that AhR agonists can decrease breast cancer proliferation and migration." (PMID 36839686, 2023). "It has previously been revealed that AhR epigenetically inactivated BRCA in breast cancer cells." (PMID 37830596, 2023). "Indeed, these miRNAs showed a protective response during cancer studies where decreased miR-548m expression suppresses cell migration and invasion by reversing the epithelial-mesenchymal transition of breast cancer via targeting aryl hydrocarbon receptor." (PMID 37457712, 2023). "Interestingly, the blockade of AhR signaling by antagonistic compounds exerts inhibitory effects on the progression of breast cancer cells." (PMID 37241719, 2023). "However, the AOP for AhR-induced breast cancer, which was based on an artificial intelligence tool, provides limited molecular insight into the KEs induced by AhR activation in breast cancer cells." (PMID 37696458, 2023). "Thus, the role of the AhR alone in breast cancer is variable and is breast cancer cell type-dependent; current evidence favors a pro-oncogenic phenotype for the AhR, but this needs to be further investigated in multiple breast cancer cell lines." (PMID 36428667, 2022). "However, it is clear that AhR ligands effect some AhR-dependent genes and pathways to promote mammary cancer, whereas there is also strong evidence that AhR agonists are potential drugs for clinical application in breast cancer therapy." (PMID 36428667, 2022). "Other significant pathways included pathways implicated in breast cancer, among them: actin cytoskeleton, the role of BRCA1 in DNA damage response, paxillin, UVA-induced MAPK, aryl hydrocarbon receptor, ILK, and the molecular mechanisms of cancer-signaling pathways." (PMID 36360779, 2022). "The pharmaceutical-derived AhR agonists identified in the screening study, including flutamide, leflunomide, mexiletine hydrochloride, nimodipine, omeprazole, sulindac and tranilast were investigated in breast cancer cells." (PMID 36428667, 2022). "Suspended ER negative BT549, MDA-MB-231 and SUM159 breast cancers cells express higher AhR levels and AhR inhibition or loss decreased pro-oncogenic pathways." (PMID 36428667, 2022). "Conversely, AhR activation by the potent agonists TCDD and DMBA was found to increase the breast cancer stem cell population and was implicated in doxorubicin resistance of MCF-7 breast cancer cells." (PMID 36588678, 2022). "A Dubrovska and his colleagues reported that CXCR4 activation could maintain the stem cell population in tamoxifen-resistant breast cancer cells through AhR signaling." (PMID 35831824, 2022). "Although the loss of AhR in mice does not affect mammary tumorigenesis, studies in breast cancer cell lines give variable results." (PMID 36428667, 2022). "Several studies have reported AhR overexpression in human breast cancer." (PMID 36588678, 2022). "RelB/AhR complex is also involved in the overexpression of CXCL8 in breast cancer." (PMID 36588678, 2022). "Moreover, the functional role of the AhR in various breast cancer cell lines is also variable and exhibits both tumor promoter- and tumor suppressor- like activity and the AhR is expressed in both ER-positive and ER-negative cells/tumors." (PMID 36428667, 2022).
breast carcinoma (continued). "Using samples from breast cancer patients, we found that AhR is frequently over-expressed in ER-negative human breast tumors, and this is closely correlated with elevated expression of the NF-кB subunit RelB and inflammatory markers such as IL-8 (CXCL1 in mouse) and COX-2." (PMID 36588678, 2022). "The overexpression of AhR and/or its increased activity has been observed in a number of tumor types, including breast cancer, lung adenocarcinoma, gastric cancer, adult T-cell leukemia, pancreatic cancer, prostate cancer, urothelial carcinoma, human glioma or medulloblastoma." (PMID 36077780, 2022). "There is also evidence that the AhR plays a pro-oncogenic role in other models of breast cancer." (PMID 36428667, 2022). "AhR activation has been shown to be involved in hematopoiesis and inflammation process especially the production of inflammatory cytokines whereas AhR repression has been shown to be beneficial in anti-cancer therapies especially for glioblastomas and breast cancers." (PMID 36176461, 2022). "It has been demonstrated that KYNA binding to AHR induces IL-6 production in breast cancer cells." (PMID 33422134, 2021). "In addition, 3-methylcholanthrene has been reported to activate EGFR/ERK/c-Fos transduction signaling through an Aryl hydrocarbon Receptor (AhR) and GPER-mediated mechanism in both breast cancer cells and Cancer-Associated Fibroblasts (CAFs)." (PMID 34831222, 2021). "This study aimed to evaluate the effect of this SFN enantiomer on phase II enzymes AhR, Nrf2, and ERα expression in breast cancer cell lines differing in ERα status (i.e., ER(+) MCF7, ER(−) MDA-MB-231) and non-tumorigenic immortalized epithelial breast cell line (MCF10A)." (PMID 33064289, 2021). "Interestingly, an increase in AhR gene expression was observed in biliverdin-treated breast cancer cells." (PMID 34924900, 2021). "This is quite interesting once it reinforces AhR as a promising target to control migration and invasion in breast cancer cells through in vitro preliminary tests, and suggests the possibility to use less or non-toxic AhR ligands that leads to similar responses." (PMID 34746229, 2021). "Furthermore, the tumor suppressive function of AhRR was confirmed in mouse PyMT-derived mammary tumor cells and human breast cancer cell lines indicating that AhRR inhibits cell proliferation and AhR-mediated apoptosis resistance." (PMID 33763068, 2021). "The aim was to study associations between intratumoral levels of AhR and aromatase, patient characteristics, including AhR and CYP19A1 genotypes, and clinicopathological features and prognosis in different treatment groups of primary breast cancer patients." (PMID 34094928, 2021). "Indeed, AhR mRNA is overexpressed in breast cancer, lung cancer, thyroid cancer, and oral squamous cell carcinoma (OSCC)." (PMID 33451095, 2021). "AhR is thus a potential target for new drugs in breast cancer." (PMID 34094928, 2021). "A small study reported that AhR might induce intratumoral aromatase and thereby stimulate estrogen-dependent breast cancer progression." (PMID 34094928, 2021). "Formation of the E-cadherin/AhR/Skp2 complex and subsequent ubiquitination of E-cadherin induced by kynurenine has been documented in lung cancer and breast cancer cells, indicating a generalized mechanism of E-cadherin suppression by kynurenine in different cancer types." (PMID 34769098, 2021). "AhR acts as an immunomodulator and is a suggested link between inflammation and breast cancer." (PMID 34094928, 2021). "As AHR and ER exhibit “cross-talk” through a number of mechanisms, with a resultant impact on breast cancer cells, it is not surprising that human trials have examined chemoprevention of breast cancer." (PMID 34660663, 2021). "The finding of overexpressed AhR in mammary cancer in rats raised the question of whether AhR is involved in breast cancer progression." (PMID 33763068, 2021).
breast carcinoma (continued). "Taxifolin suppressed breast cancer by regulating the AhR and Cytochrome P450 CYP1A1 pathway." (PMID 34113483, 2021). "Similarly, many previous studies have identified AhR as a marker of poor prognosis in various cancers, such as glioblastoma, breast cancer, and renal clear cell carcinoma." (PMID 34290693, 2021). "AHR inhibits redox homeostasis and modulates the tumor promoting microenvironment in breast cancer." (PMID 34784845, 2021). "Finally, AhR has been shown to prevent tumor development through the regulation of several tumor suppressor miRNAs (microRNAs) in breast cancer, prostate cancer, and malignant tumors of the endometrium." (PMID 33451095, 2021). "In vitro studies suggest that AhR activation induces intratumoral aromatase, which in turn increases intratumoral estrogen synthesis and proliferation while at the same time inhibiting the ER pathway in breast cancer cells." (PMID 34094928, 2021). "Indeed, TCDD, the highly toxic AhR agonist, cannot be used in the clinic to specifically target AhR, despite its positive effect against breast cancer, by disrupting the CXCR4/CXCL12 pathway, or ovarian cancer cells." (PMID 33451095, 2021). "Next, we investigated whether a modulation of AhR activity affects drug-induced apoptosis consistently in human triple negative MDA-MB 231 breast cancer cells." (PMID 33763068, 2021). "In the current study we have examined several AhR-driven outcomes, to determine whether AhRR functionally opposes AhR and is able to suppress the development of mammary tumors." (PMID 33763068, 2021). "The role of the AHR in breast cancer is even more sinister than this simple induction process." (PMID 32814815, 2020). "Hence, this study provides insights into synergistic and other combinatory effects of Alternaria toxins in natural co-occurrence scenarios in the context of AhR signalling pathway activation in breast cancer cells." (PMID 32659980, 2020). "These pieces of evidence show that AhR can be a therapeutic target in breast cancer." (PMID 32085612, 2020). "Importantly, AHRhigh/ALDHhigh breast cancer CSCs were significantly more efficient at initiating tumors than AHRlow/ALDHlow cells, and AHR knockdown with siRNA significantly reduced tumor-initiating capacity, a sine qua non of CSCs." (PMID 33396563, 2020). "Previously, ATX-II was found to increase CYP 1 transcription and activity in oesophageal cancer cells starting at a concentration of 0.05 μM and 0.1 μM, respectively, indicating a higher sensitivity to AhR activation compared to the breast cancer cell line MCF-7." (PMID 32659980, 2020). "Univariate analysis of the GPR30 mRNA expression levels, the AhR mRNA expression levels and the GPR30/AhR mRNA expression signature with regards to overall survival (OS) in different subclasses of the 1,877 breast cancer samples of the Kaplan-Meier plotter (KMP) cohort." (PMID 32670863, 2020). "Thus, their findings indicate that resveratrol prevents breast cancer development by modulating BRCA1 expression via AhR signaling regulation." (PMID 32183060, 2020). "Increased nuclear AHR localization was positively correlated with a higher tumor grade, more poorly differentiated cells, and/or poor prognosis in prostate, oral, and breast cancers, suggesting that the AHR may be contributing to increasing cancer aggression." (PMID 33396563, 2020). "Furthermore, virtual screening studies indicated that emodin was a potent aryl hydrocarbon receptor (AhR) agonist in chemotherapy for breast cancer." (PMID 33542691, 2020). "Besides, extensive research revealed that AhR pathway activation disparately impacts mammary tumorigenesis and assigned a major role in breast cancer progression towards metastasis to AhR activation." (PMID 32659980, 2020).